ZNF467 (zinc finger protein 467)
Description:
Transcription factor that promotes adipocyte differentiation and suppresses osteoblast differentiation in the bone marrow. Enhances the osteoclast-supporting ability of stromal cells. Binds with STAT3 the consensus sequence 5'-CTTCTGGGAAGA-3' of the acute phase response element (APRE). Transactivates several promoters including FOS, OSM and PPARG. Recruits a histone deacetylase complex (By similarity).
Synonyms: EZI; Zfp467
Tractability: PROTAC: UniProt records ubiquitination sites on it.
Gene: Protein-coding gene on chromosome 7 (149,764,175 to 149,776,519, reverse strand). Ensembl gene ENSG00000181444.
Subcellular location: Nucleus
Subcellular location (Human Protein Atlas): Mitochondria
Pathways (Reactome):
Developmental Biology: Transcriptional regulation of white adipocyte differentiation
Gene Ontology:
Molecular function: protein binding; DNA-binding transcription factor activity, RNA polymerase II-specific; RNA polymerase II cis-regulatory region sequence-specific DNA binding; DNA binding
Biological process: regulation of transcription by RNA polymerase II
Cellular component: nucleus
Genetic constraint (gnomAD): Loss-of-function variants: 51 observed, 35.72 expected, observed/expected ratio (o/e) 1.43, 90% interval 1.14 to 1.79. The synonymous counts are far from expectation, so gnomAD's model fits this gene poorly and the ratio says little. Missense variants: 992 observed, 720.12 expected, observed/expected ratio (o/e) 1.38, 90% interval 1.31 to 1.45. Synonymous variants: 416 observed, 310.15 expected, observed/expected ratio (o/e) 1.34, 90% interval 1.24 to 1.46.
Homologues: Orthologues: chimpanzee ZNF467 (99% identical), macaque ZNF467 (96% identical), guinea pig ZNF467 (85% identical), mouse Zfp467 (85% identical), rat Zfp467 (84% identical), rabbit ZNF467 (83% identical), dog ZNF467 (83% identical), pig ZNF467 (81% identical). Paralogues in human: ZNF17 (31% identical), ZNF287 (31% identical), ZNF530 (30% identical), ZNF416 (30% identical), ZNF214 (29% identical), ZNF697 (28% identical), ZKSCAN7 (28% identical), ZNF527 (28% identical), ZNF417 (27% identical), ZNF587 (27% identical), ZNF852 (27% identical), ZNF776 (27% identical), and 38 more.
Diseases named in the same sentence as ZNF467 in open-access papers:
ZNF467 is named in the same sentence as 16 diseases in open-access papers, as found by Europe PMC text mining. Sharing a sentence is not in itself a finding about the gene and the disease. The quoted sentences say what the papers report.
prostate carcinoma (2 papers, 2021 to 2022). A carcinoma that arises from epithelial cells of the prostate gland. "As results, high KCTD4 expression, low THBS2 expression, and high ACPP expression were associated with favorable BCRFS of prostate cancer patients; and high expression levels of HOPX, TMEM132A, and ZNF467 were associated with shorter MFS of prostate cancer patients." (PMID 36195908, 2022). "In agreement, ZNF467 gene expression can distinguish low (≤6) from high (≥8) Gleason score prostate tumors in a Fred Hutchinson Cancer Research Center prostate cancer dataset (381 localized and 27 metastatic prostate tumors)." (PMID 33585078, 2021). "Our study not only highlights genes modulated by GHSROS, but also genes (such as ZNF467, CHRDL1, and PPP2R2C) that may be generally relevant to prostate cancer progression." (PMID 33585078, 2021).
atherosclerosis (1 paper, 2025). A disease characterized by the build-up of fatty material and calcium deposition in the arterial wall resulting in partial or complete occlusion of the arterial lumen. "Using a Venn diagram to identify the shared genes, we identified six candidate downstream molecules potentially regulated by AP‐1 and involved in vascular endothelial dysfunction and atherosclerosis induced by OSS: NR4A1, ZNF467, LGAL59, OAS1, OAS2, and TGM2." (PMID 40492401, 2025).
breast carcinoma (1 paper, 2021). "ZNF467 has not been functionally characterized, however, a recent study suggests that it is a transcription factor which clusters in close proximity to the androgen receptor in a network associated with breast cancer risk, indicating that ZNF467 and AR regulate similar pathways." (PMID 33585078, 2021). "ZNF467 expression is also elevated in chemotherapy-resistant ovarian cancer and breast cancer cell lines." (PMID 33585078, 2021).
COVID-19 (1 paper, 2024). A disease caused by infection with severe acute respiratory syndrome coronavirus 2. "Similarly, we found the relevant evidence of alteration or association of transcription factors CENPA, DDIT3, JUNB, TFDP1, ZBTB16, ZNF467 for the alteration of diverse cellar process and function to develop the COVID-19 pathogenesis and associated respiratory disorders." (PMID 38365632, 2024).
metastatic tumors (1 paper, 2021). "DIRAS1, FBXL16, TP53I11, TFF2, and ZNF467 were upregulated in both metastatic tumors and GHSROS-overexpressing PC3 and LNCaP cells, while AASS, CHRDL1, CNTN1, IFI16, and MUM1L1 were downregulated." (PMID 33585078, 2021).
pulmonary fibrosis (1 paper, 2024). Chronic progressive interstitial lung disorder characterized by the replacement of the lung tissue by connective tissue, leading to progressive dyspnea, respiratory failure, or right heart failure. "The hypermethylation of zinc finger protein 467 (ZNF467) gene downregulate its protein expression in pulmonary fibrosis, thereby decreasing the activation of peroxisome proliferator-activated receptor gamma (PPARγ)." (PMID 38915445, 2024).
infection (1 paper, 2024). The state of being infected such as from the introduction of a foreign agent such as serum, vaccine, antigenic substance or organism. "For example, the promoter region of ZNF467 had increased accessibility (infection-biased OCRs) and associated increased gene expression." (PMID 38862613, 2024).
ZNF467 also shares sentences with these, for which no sentence is quoted: cancer (2 papers); brain tumors (1); Obesity (1); osteoporosis (1); ovarian carcinoma (1); prostate tumors (1); respiratory disorders (1); sarcoma (1); tumor (1).